RN7SL30P (RNA, 7SL, cytoplasmic 30, pseudogene)
Gene: Miscellaneous RNA gene on chromosome 9 (125,512,902 to 125,513,207, reverse strand). Ensembl gene ENSG00000243845.
Homologues: Orthologues: chimpanzee Metazoa_SRP (99% identical), macaque Metazoa_SRP (90% identical). Paralogues in human: RN7SL1 (82% identical), RN7SL2 (82% identical), RN7SL3 (81% identical), RN7SL329P (80% identical), RN7SL709P (79% identical), RN7SL45P (78% identical), RN7SL479P (78% identical), RN7SL665P (78% identical), RN7SL113P (78% identical), RN7SL464P (77% identical), RN7SL712P (77% identical), RN7SL732P (77% identical), and 704 more.